AR (androgen receptor)
Diseases named in the same sentence as AR in open-access papers (continued):
Sharing a sentence is not in itself a finding about the gene and the disease.
cancer (continued). "Animal studies have demonstrated that AR acts as a suppressor of cancer progression by inhibiting cancer cell invasion and by promoting cell detachment-induced apoptosis (anoikis)." (PMID 27340775, 2016). "A similar percentage was seen in another study which also confirmed that ER-positive cancers had a much higher AR positivity at 83%." (PMID 26797644, 2016). "TPX2 knockdown reduced prostate-specific antigen (PSA) expression in PCa cell lines, indicating that TPX2 regulates AR signaling in PCa, and induced cell cycle arrest, apoptosis, and the inhibition of cell proliferation and invasion in multiple other cancers." (PMID 27626693, 2016). "These therapies inactivate the AR to halt transcription of androgen responsive target genes, but cancer cells often develop resistance." (PMID 27223260, 2016). "Luminal androgen receptor is a subtype in which androgen signalling plays an important role in the cancer cell growth and progression." (PMID 26757422, 2016). "PD-L1 expression was significantly more common in cancers with lymphocytic infiltrates (OR, 3.3; 95% CI 1.1–10.4) and androgen receptor expression (OR, 3.2; 95% CI 1.4–7.5), and less common in tumors with lymphovascular invasion (OR 0.41; 95% CI 0.18–0.92)." (PMID 28721372, 2016). "Similar to our previous study, the internalization of exosomal CLUGFP (derived from the LNCaP cell line) into cancer and benign prostate cell lines with different AR phenotypes was clearly demonstrated." (PMID 26840259, 2016). "Androgen receptor (AR) is a member of the nuclear receptor (NR) superfamily regulating the expression of genes that are important in development, differentiation, and cancer progression, especially of the prostate." (PMID 26918604, 2016). "We observed that in the first ~7 months, castration led to time-dependent increases in PSA−/lo cells, loss of AR and PSA expression, increased expression of cancer stem cell markers, and many other molecular changes." (PMID 26871947, 2016). "We found that TNBCs that express the AR are also threefold more likely to express PD-L1 on cancer cells." (PMID 28721372, 2016). "The survival of malignant tumors that arise from the prostate gland is dependent on the androgen receptor (AR), a classical nuclear steroid receptor that binds androgen and activates gene transcription." (PMID 27028864, 2016). "One mechanism for PCa to become castration resistant is due to the amplification and overexpression of AR gene enabling the cancer cells to grow with very low levels of androgen." (PMID 26928323, 2016). "Of the 73 TNBC from BRCA1 carriers, 3 (4.1%) expressed both, with one cancer having weak AR staining (1–10% cells) and 2 having >10% AR staining." (PMID 28721372, 2016). "LNCaP cells are widely used as an approximation to androgen sensitive cancer and 22Rv1 cells are considered one model of AR positive CRPC." (PMID 27378372, 2016). "Among 194 TNBC with IHC staining results for AR, 35 (18.0%) expressed the AR, with at least 1% of cancer cells staining, whereas 22 (11.3%) demonstrated >10% of cancer cells staining." (PMID 28721372, 2016). "Several studies have reported that natural compounds or herbal extracts inhibit cancer cell growth and induce apoptosis by downregulating AR signaling." (PMID 27399684, 2016). "(E) Once PC progresses to NE cancer, PC cells will lose AR, becoming resistant to any drug that targets the AR." (PMID 27542219, 2016). "Due to the crucial role of the transcriptional activation of AR in cancer development, an effective therapeutic target is essential to cure patients with CRPC." (PMID 27602760, 2016). "Although TNBCs from BRCA1 carriers less frequently express the AR, on multivariable analysis the factors that predicted >10% AR expression were older age and lower grade, whereas PD-L1 expression on cancer cells significantly predicted ⩾1% AR expression." (PMID 28721372, 2016).
cancer (continued). "Consistent with the probability that males have higher testosterone levels than females and that binding of androgen stabilize AR protein, AR protein showed significantly higher expression in cancers of male compared to female patients." (PMID 26814892, 2016). "We chose AR because in addition to its well-known role in cancer and male reproductive function, it also has a role in neurogenesis." (PMID 27782803, 2016). "In a recent study, DIM also showed depression of miR-34a and inhibition of cancer growth via AR signaling in vivo." (PMID 27231938, 2016). "To elucidate the biological relevance of these potential AR activators in human cancer, we used Ensemble 82 to search for human homologs to the 77 Drosophila genes and identified 172 human genes." (PMID 27363033, 2016). "Our results showed that while MYC was only expressed in a few basal cells in NHPrE1/EV grafts, many more MYC-positive cells were detected in the carcinomas that formed in NHPrE1/AR grafts." (PMID 27611945, 2016). "Surprisingly, high levels of AR activity have been associated with better outcomes in estrogen receptor (ER)-positive cancers but with poor prognosis in ER-negative and HER2+ cancers." (PMID 25592291, 2015). "Residual androgen receptor (AR)-signaling and presence of cancer stem-like cells (SCs) are the two emerging paradigms for clinically challenging castration-resistant prostate cancer (CRPC)." (PMID 25965834, 2015). "Strong HOXB13 expression was found in 17% of cancers with strong AR expression, but only in 1.3% of AR-negative tumors." (PMID 25825985, 2015). "The present study was designed to evaluate the possibility that these proteins are significant in cancer invasion and staging by comparing the expression of AR and MMP in HCC tissues with that in tissues adjacent to the HCC." (PMID 25667651, 2015). "Disruption of NRIP1 function has been reported to lead to hyperactivation of AR signaling, and variants in NRIP1 have been linked to risk in breast, endometrial, and other cancers." (PMID 26485759, 2015). "The majority of castration-resistance cancers persist in the expression of the androgen receptor (AR), as well as androgen-dependent genes." (PMID 26008968, 2015). "AR-V7 protein expression was low relative to AR-FL in androgen-deprived VCaP cells and mice xenografted with castration-resistant VCaP cancer cells." (PMID 25705125, 2015). "ATAD2 has been described as an estrogen and androgen responsive gene in hormone dependent cancer cells and a co-activator for full activity of ER and AR, contributing to cancer related proliferation." (PMID 26308378, 2015). "A single KDM4B methylase, then, can have opposite effects on AR signaling and disease progression in different types of cancer." (PMID 26397136, 2015). "Recent work has identified complex feedback regulation between mTORC1 inhibition and growth factor-dependent PI3 kinase activity in cancer cells, and cancer cell responses to both receptor tyrosine kinase and androgen receptor stimulation." (PMID 26295809, 2015). "Although targeting androgens through ablation is therefore an effective initial treatment strategy for advanced cancer, most reoccur by refractory reactivation of epithelial AR." (PMID 25965833, 2015). "AR-positivity, defined as nuclear staining in at least 10% of cancer cells, has been detected in approximately one-third of TNBCs and is associated with good prognosis." (PMID 25973541, 2015). "The survival of malignant tumors arising from the prostate gland is dependent on the androgen receptor (AR), a classical nuclear steroid receptor that binds androgen and activates gene transcription." (PMID 25730905, 2015). "Additional studies are necessary to clarify the roles of KDM4 epigenetic regulators, AR, and downstream target genes in EC and in other types of cancer." (PMID 26397136, 2015).
cancer (continued). "As loss of PTEN and TGFBR2 from prostate has been shown to result in castration-resistant cancer with metastases, we assume that miR-216a would play a critical role in the modulation of AR signaling and development of endocrine resistance." (PMID 26506397, 2015). "This can be achieved by either using drug combinations that target AR-signaling and cancer SC-signaling simultaneously, or by identifying and targeting effector proteins common to these signaling cascades." (PMID 25965834, 2015). "That high-level PSA can be found in the majority of AR-negative cancers can be explained by AR-independent up regulation of PSA by the mitogen activated protein (MAP) kinase pathway." (PMID 25825985, 2015). "Although it is interesting that two different KDM4 proteins act via two distinct mechanisms to promote EC in both low and high AR cell lines, similar effects have been observed in other cancers." (PMID 26397136, 2015). "For instance, the cancer can acquire the ability to synthesize AR ligands, phosphorylate AR or, through alternative splicing, create a constitutively active AR." (PMID 26010887, 2015). "Activated AR is a potent stimulator of cell cycle progression from G1 to S phase in cancer cells through the Cyclin D1/retinoblastoma/E2F1 axis." (PMID 25749045, 2015). "It is particularly interesting that in CRPC where aberrant AR activation is often observed, the cancer cell can be still fueled by anabolic biosynthesis." (PMID 26690121, 2015). "We demonstrated that fatostatin displayed anti-cancer activity by interrupting SREBP transcriptional activity in AR-positive PCa cells." (PMID 26512780, 2015). "In this study using patient-derived prostate epithelial cultures (PPECs) and over three hundred clinical samples, we identify CIP2A to be a common denominator for AR and cancer SC-signaling functionality." (PMID 25965834, 2015). "We also identified a significant decrease in invasion of the cancer cells through DHT-treated PShTert-AR gelatin matrix in comparison to matrix conditioned by vehicle treated PShTert-AR or DHT-treated PShTert-ctrl cells." (PMID 25965833, 2015). "This review describes patterns of AR expression in a spectrum of cancers, and the potential to exploit this knowledge in the clinical therapeutic setting." (PMID 25595907, 2015). "This latter result suggests that low stromal AR reduces apoptosis of primary cancer cells in response to androgen deprivation in vivo." (PMID 25965833, 2015). "High-level PSA was found in 65.9% of AR-negative cancers, but only in 39% of strongly AR-positive tumors (p < 0.0001)." (PMID 25825985, 2015). "Human cancer cells combined with both PShTert-AR and PShTert-controls formed phenotypically similar ductal structures that stained positive for the human-specific epithelial marker p63/CK8.18." (PMID 25965833, 2015). "As AR complexes with histone lysine demethylases (KDMs) to regulate AR target genes in human cancers, we also investigated if the same mechanism is present in the ovine placenta." (PMID 25675430, 2015). "Instead, we found in grafts containing AR positive myofibroblasts that cancer cells exhibit increased apoptosis following castration." (PMID 25965833, 2015). "This indicates that the AR LBD is dispensable for AR transcriptional activity and continued contribution towards cancer progression." (PMID 26196517, 2015). "In the castrate-resistant cancer cells, there is low possibility for ARfl still functioning actively with ligand depletion, but another story for constitutive active AR-Vs." (PMID 25481872, 2015). "Enforced expression of miR-34a in PC cells resulted in reduced expressions of the AR, PSA, and Notch-1 concomitant with inhibition of the self-renewal capacity, a phenotype associated with cancer stem cells." (PMID 26690121, 2015).
cancer (continued). "Our patient and LNCaP xenograft data confirmed that androgen receptor regulation of ASCT2 contributes to its expression in untreated/primary cancer and that under androgen‐deprivation therapy, ASCT2 levels decrease." (PMID 25693838, 2015). "Using the ENZ-resistant MR49F and androgen-independent LNCaP95 cells models, we show that ICRF187 and ICRF913 potently inhibit AR signaling, cancer cell proliferation and CRPC xenograft growth." (PMID 26009876, 2015). "It is therefore suggested that androgen-mediated activation of AR signaling would promote bladder tumorigenesis and cancer progression." (PMID 25557268, 2014). "In fact, the majority of PCa specimens in the setting of relapse from hormonal therapy expresses AR and these cancers remain dependent on AR signaling for proliferation and survival in the presence of castrate levels of androgens." (PMID 24681825, 2014). "Findings here presented support the role of AR in suppressing proliferation and stimulating migration of stromal cells, with implications for current approaches to cancer therapy." (PMID 25646090, 2014). "The c-Myc protein also contributes to metabolic adaptations, especially the Warburg effect, at many of the same steps in metabolic pathways as the AR in PCa cells and regulates many glycolytic enzymes in cancer cells." (PMID 25271736, 2014). "Following analyses showed that in molecular apocrine cancers there is a cross talk between AR and HER2 pathway with a trend of poor outcome." (PMID 24978437, 2014). "Gene expression was analyzed using xenograft models of different PCas and enhanced AR mRNA expression was found to be a common factor of acquired ADT-resistance in many cancer cell strains, showing that cells also respond to a low concentration of androgen." (PMID 25279351, 2014). "Conversely, restoration of AR in stromal cells stimulates cancer progression, supporting a differential role of AR in PCa depending on its location." (PMID 24744780, 2014). "Upon reviewing the background information, we have inclined to consider that circulating androgens would be responsible for AR-mediated gender difference in bladder tumorigenesis and cancer progression." (PMID 25557268, 2014). "One of the mechanisms implicated in development of castration resistant PCa is deregulation of the AR signaling axis, leading to selection of mutant AR that promotes survival and proliferation of cancer cells." (PMID 24586868, 2014). "Considering TNBC cases only, AR-positive cases were less frequent in the African American cancer cohort in comparison to cancers of white patients (16.7% vs 25.5%); the 5NP group showed AR-positive cases more frequently than Core Basal tumors (p = ns)." (PMID 24505496, 2014). "Molecular evidence has indicated that AR signals promote bladder carcinogenesis as well as cancer progression." (PMID 25557268, 2014). "In following section we discuss AR regulation by subsets of miRNA and their expression patterns in cancer cells." (PMID 24739220, 2014). "Altogether, these findingsindicate that further exploration of the androgen/AR axis should be pursuedin stromal and epithelial compartment of these cancers." (PMID 25476896, 2014). "Nuclear localization of GAK and the AR was detected in the nuclei of cancer cells from all GAK-positive surgical specimens (n = 4 patients with a Gleason score ≤7 and n = 5 patients with a Gleason score ≥8)." (PMID 24971999, 2014). "The idea of using small molecule inhibitors of heat shock protein 90 (Hsp90) as therapeutic tools in SBMA originates from cancer studies which revealed that AR is an Hsp90 client and requires heat shock proteins for proper functioning." (PMID 25132814, 2014). "Some studies using CRPC cancer tissue have investigated intraprostatic testosterone or the active metabolites in quantities, which is thought to be sufficient to stimulate AR-mediated gene expression." (PMID 25279351, 2014).
cancer (continued). "HER2-positive and ER/PR-positive carcinomas showed higher prevalence of AR positive cases than TNBCs." (PMID 24505496, 2014). "Our study does not point to a particular prognosis or therapy response of HR-/AR + carcinomas, as pCR rate and survival times were quite similar to those in HR- tumors without AR expression." (PMID 25070172, 2014). "Introduction.The aim was to evaluate the changes of androgen receptor (AR) expression quantitatively and to identify influence of AR on cancer related survival markers in LNCap cell line." (PMID 23476140, 2013). "After ADT, remaining cancer cells in CR-TSGs derived from HRPCa-2 demonstrated similar histological features and biomarkers to those in control TSGs, including expression of AR." (PMID 23985008, 2013). "Among the many identified androgen-regulated genes, sGCα1 (soluble guanylyl cyclase α1) appears to play a pivotal role in mediating the pro-cancer effects of androgens and androgen receptor." (PMID 23724033, 2013). "Human prostatic adenocarcinoma, a cancer highly resistant to standard therapies, is reliant on AR activity for growth and survival." (PMID 24350055, 2013). "Castration-resistant cancer cells remaining in TSGs showed upregulated expression of androgen receptor target genes, as occurs in castration-resistant prostate cancer (CRPC) in humans." (PMID 23985008, 2013). "Previous studies have extensively shown that transcriptional regulation by AR drives prostatic differentiation during development and oncogenic transformation during cancer (Heinlein & Chang 2004, Lamont & Tindall 2011)." (PMID 23997240, 2013). "miRNA decreased with AR expression and growth-promoting effect in cancers with increased expression (p<0.05)." (PMID 24391862, 2013). "miRNA increased with AR expression and inhibitory effect in cancers with increased expression (p<0.05)." (PMID 24391862, 2013). "Androgen receptor (AR) is the essential mediator of androgen action and plays an important role in regulating prostate development and differentiation, as well as cancer cell growth and progression." (PMID 23734213, 2013). "Majorities of PCa are dependent on AR signaling—even as they progress into castration-resistant state; AR continues to remain the favorite target for cancer therapy." (PMID 26877888, 2013). "This work strengthens our findings and suggests p68 is possibly working as a ‘coupling’ factor to facilitate not only AR-regulated transcription in PCa, but other nuclear transcriptional factors in alternative cancer types." (PMID 23349811, 2013). "AR expression was similar in ER-negative cases in both age groups; however, it was significantly higher in the older group of patients with ER-positive cancer (P = 0.0007)." (PMID 24403250, 2013). "The proto-oncogene Myc is well known to be involved in cancer formation and it also participates in AR transcription, acting as a predictor of biochemical recurrence after radical prostatectomy (RP)." (PMID 23738079, 2013). "In the present study, however, the presence of AR was found to increase cancer cell chemoresistance and ABCG2 expression." (PMID 23599788, 2013). "These recent observations provide insight into the heterogeneity observed in ER and AR driven cancers." (PMID 23420418, 2013). "While nearly all primary cancer patients showed normal AR status, over 70% of Met/CRPC patients demonstrated various degrees of AR gene copy number gain." (PMID 24098661, 2013). "AR gene amplification is observed in approximately 80% of the CRPCa cases, being the most common genetic alteration in this type of cancer." (PMID 23738079, 2013). "Taken together, the results of the siRNA knockdown and matrigel invasion assays strongly suggest that up-regulation of our set of AR-target genes contributes to a more aggressive cancer phenotype (such as invasiveness) in AA cancers." (PMID 23365759, 2013).